SHQ1 (SHQ1, H/ACA ribonucleoprotein assembly factor)
Description:
Required for the quantitative accumulation of H/ACA ribonucleoproteins (RNPs), including telomerase, probably through the stabilization of DKC1, from the time of its synthesis until its association with NOP10, NHP2, and NAF1 at the nascent H/ACA RNA.
Synonyms: FLJ10539; Shq1p; DYT35; GRIM-1; NEDDS
Tractability: PROTAC: ubiquitination databases record sites on it; its protein half-life has been measured.
Gene: Protein-coding gene on chromosome 3 (72,749,277 to 72,861,914, reverse strand). Ensembl gene ENSG00000144736.
Subcellular location: Cytoplasm, cytosol; Nucleus, nucleoplasm
Subcellular location (Human Protein Atlas): Nucleoplasm
Pathways (Reactome):
Cell Cycle: Telomere Extension By Telomerase
Gene Ontology:
Molecular function: protein binding
Biological process: protein-RNA complex assembly; telomerase RNA localization to Cajal body; box H/ACA snoRNP assembly
Cellular component: Cajal body; cytoplasm; nucleolus; nucleoplasm; cytosol
Genetic constraint (gnomAD): Loss-of-function variants: 47 observed, 48.36 expected, observed/expected ratio (o/e) 0.97, 90% interval 0.77 to 1.24. The upper end of that interval is the gene's LOEUF score, 1.24, which puts it in group 5 of 6, group 1 being the genes least tolerant of losing a copy. Missense variants: 694 observed, 679.89 expected, observed/expected ratio (o/e) 1.02, 90% interval 0.96 to 1.09. Synonymous variants: 231 observed, 253.2 expected, observed/expected ratio (o/e) 0.91, 90% interval 0.82 to 1.02.
Homologues: Orthologues: chimpanzee SHQ1 (99% identical), macaque SHQ1 (95% identical), dog SHQ1 (83% identical), rabbit SHQ1 (81% identical), pig SHQ1 (81% identical), guinea pig SHQ1 (80% identical), rat Shq1 (75% identical), mouse Shq1 (75% identical), tropical clawed frog shq1 (55% identical), zebrafish shq1 (48% identical), Caenorhabditis elegans Y48A5A.1 (26% identical), Drosophila melanogaster CG10055 (23% identical).
Diseases named in the same sentence as SHQ1 in open-access papers:
SHQ1 is named in the same sentence as 27 diseases in open-access papers, as found by Europe PMC text mining. Sharing a sentence is not in itself a finding about the gene and the disease. The quoted sentences say what the papers report.
prostate carcinoma (4 papers, 2011 to 2022). A carcinoma that arises from epithelial cells of the prostate gland. "Integrative genomic profiling reveals that the frequency of SHQ1 deletion in chromosome 3p of prostate cancer and cervical invasive carcinomas are 14.7% and 61%, respectively." (PMID 32522979, 2020). "More importantly, a very recent study reported deletion of SHQ1 locus in primary prostate cancers suggesting it to be a cooperative tumor suppressor." (PMID 21931644, 2011). "Recent studies have indicated that SHQ1 inhibits prostate cancer growth and metastasis." (PMID 32522979, 2020). "A multigenic locus at 3p13-14, spanning FOXP1 to SHQ1, is commonly deleted in prostate cancer and lost broadly in a range of cancers but has unknown significance to oncogenesis or prognosis." (PMID 29057879, 2017). "SHQ1 cooperates with PTEN to inhibit the development and metastasis of prostate cancer in mice." (PMID 32522979, 2020). "However, SHQ1 is highly expressed in T-ALL and promotes the development of T-ALL10, which is contrary to previous reports of prostate cancer and cervical cancer." (PMID 32522979, 2020).
Dystonia (3 papers, 2023 to 2025). An abnormally increased muscular tone that causes fixed abnormal postures. "Compound heterozygous variants in SHQ1 have recently been linked to early onset dystonia and other neurological features; when expressed in yeast cells, these mutated forms of SHQ1 impaired formation of H/ACA snoRNPs and ribosomes." (PMID 37818102, 2023). "More recent reports have linked SHQ1 mutations to global developmental delays, seizures and dystonia." (PMID 37818102, 2023). "Given that SHQ1 variants altering formation of H/ACA snoRNPs and ribosomes are linked to dystonia, this syndrome should be added to the list of ribosomopathies." (PMID 37818102, 2023). "Compound heterozygous mutations in SHQ1 have been associated with a rare and severe neurological disorder characterized by global developmental delay (GDD), cerebellar degeneration coupled with seizures, and early-onset dystonia." (PMID 36810590, 2023). "Screening our data for proposed dystonia candidate genes identified presumably pathogenic variants in CHD6, KCNN2, KLC1, NR4A2, and ZMYND11, but not in others, for example, ATP5F1B, ACBD6, CIZ1, SHQ1, and SPTBN1." (PMID 40533913, 2025).
cerebellar degeneration (2 papers, 2017 to 2023). Degeneration of the cerebellum. "Variants of human SHQ1 have been linked to neurodevelopmental deficiencies; here we focused on two compound heterozygous mutations identified in a child showing a severe neurological disorder comprising cerebellar degeneration." (PMID 37818102, 2023).
developmental delay (2 papers, 2023). "In conclusion, our study reports the first SHQ1 homoallelic variant in three patients from two separate unrelated families who presented with global developmental delay, ataxia, and seizure disorder." (PMID 36810590, 2023).
prostate tumor (2 papers, 2011 to 2017). "It is unknown whether this region has a tumor suppressive function, but more than 12% of primary prostate tumors show copy number loss of the 3p13-14 region from FOXP1 to SHQ1 (termed FOXP1-SHQ1 deletion) and 15% show copy number loss of the individual FOXP1 or SHQ1 genes that bound the deletion." (PMID 29057879, 2017). "The fact that all the prostate tumors are enriched for deletion of the entire locus or for deletion of both FoxP1 and Shq1, rather than selective deletion of FoxP1 and/or Shq1 individually, suggests that at least two genes in the interval play a role in restraining tumor progression in this model." (PMID 29057879, 2017).
acute lymphoblastic leukemia (1 paper, 2020). Leukemia with an acute onset, characterized by the presence of lymphoblasts in the bone marrow and the peripheral blood. "SHQ1 facilitates MYC RNA splicing to promote T-acute lymphoblastic leukemia (T-ALL) development." (PMID 32522979, 2020). "A recent study have indicated that SHQ1 is highly expressed in T-acute lymphoblastic leukemia (T-ALL) and promotes the development of T-ALL through promoting MYC RNA splicing." (PMID 32522979, 2020).
acute myeloid leukemia (1 paper, 2018). Acute myeloid leukemia (AML) is a group of neoplasms arising from precursor cells committed to the myeloid cell-line differentiation. "To evaluate the role of SHQ1 in different tumor types, we inactivated SHQ1 in B-ALL (RS4;11), acute myeloid leukemia (AML) (HL-60), chronic myeloid leukemia (CML) (K562), and lung cancer (A549) cell lines." (PMID 30323192, 2018).
bone marrow failure syndrome (1 paper, 2017). "Hence, SHQ1 screening may be warranted in patients with inherited bone marrow failure syndromes." (PMID 29178645, 2017).
COVID-19 (1 paper, 2025). A disease caused by infection with severe acute respiratory syndrome coronavirus 2. "By 6 weeks post-inclusion (T2), COVID-19 hypermethylation of genes with lowest p-value included NXN, FMNL2, ZBTB46, SLC35F3, and SHQ1, and the hypomethylated genes included ELMO1, XBP1, GRIK1, TNFAIP8, and SH3BP5." (PMID 41227320, 2025).
hepatocellular carcinoma (1 paper, 2020). A malignant tumor that arises from hepatocytes. "We report here that SHQ1 promotes tumor apoptosis and chemo-sensitivity in hepatocellular carcinoma (HCC) cells." (PMID 32522979, 2020). "We next determined if the expression of SHQ1 is somehow altered in a tissue microarray comprising 80 primary hepatocellular carcinomas (HCC)." (PMID 32522979, 2020).
leukemia (1 paper, 2018). A malignant (clonal) hematologic disorder, involving hematopoietic stem cells and characterized by the presence of primitive or atypical myeloid or lymphoid cells in the bone marrow and the blood. "Immunohistochemical (IHC) staining confirmed that SHQ1 deficiency significantly decreased human CD45+ leukemia burden and cell proliferation (reflected by proliferating cell nuclear antigen (PCNA) staining) in the spleen." (PMID 30323192, 2018). "Consistently, mice bearing SHQ1-deficient cells manifested ameliorated splenomegaly and more reddish bones, as well as suppressed CD45+ leukemia cell dissemination in the BM and spleen." (PMID 30323192, 2018). "Using three individual normal thymus specimens as control, we further verified these findings in 11 Chinese T-ALL patient samples, and found that SHQ1 was generally more abundant in leukemia cells with enhanced NOTCH1 activation, as judged by ICN1 production." (PMID 30323192, 2018). "In addition, we also analyzed SHQ1 function in normal murine thymus and murine T-ALL cells, and consistently found heightened cell death in leukemia cells upon SHQ1 inactivation as compared to normal thymocytes." (PMID 30323192, 2018).
lung carcinoma (1 paper, 2018). "However, SHQ1 deficiency in lung cancer cell line A549 induces minimal cell death and higher expression of SHQ1 is associated with better overall survival in lung cancer patients." (PMID 30323192, 2018). "B-ALL, AML, and CML cells were all sensitive to SHQ1 inactivation, whereas lung cancer cells were not." (PMID 30323192, 2018).
T-cell lymphoma (1 paper, 2018). "Similarly, SHQ1 plays an essential role in B-ALL, AML, and CML cells, and high SHQ1 expression correlates with poor prognosis in T-cell lymphoma and AML." (PMID 30323192, 2018).
tumor (7 papers, 2011 to 2024). "Given that the induction of ER stress is a classic inducer of intrinsic apoptosis, we next used flow cytometry to determine the extent of apoptosis in the control and SHQ1-deficient TM-treated tumor cells." (PMID 32522979, 2020). "Based on our in vitro results, we next examined if the loss of SHQ1 promotes tumor growth in vivo." (PMID 32522979, 2020). "Consistently, loss of SHQ1 resulted in a significant increase in tumor weight." (PMID 32522979, 2020). "SHQ1 deficiency was sufficient to accelerate tumor growth after injection with TM." (PMID 32522979, 2020). "In Moreover, the splicing regulatory gene SHQ1 has been shown to facilitate the survival of T-ALL tumor cells via the NOTCH1-SHQ1-MYC pathway, in addition to its involvement in regulating aerobic glycolysis." (PMID 39044280, 2024). "Immunohistochemical analyses revealed that the expression of GRP78 was significantly decreased in SHQ1-KD tumors.Tumor xenografts were stained with a PCNA antibody for detecting proliferation." (PMID 32522979, 2020). "Our study thus demonstrates a SHQ1-mediated ER-stress response feedback loop that promotes tumor sensitivity to chemotherapeutics." (PMID 32522979, 2020). "The expression of SHQ1 was lower in HCC tumor tissues than that in adjacent non-tumor tissues, suggesting tumors tend to lose SHQ1 for promoting their growth." (PMID 32522979, 2020). "Experiments with HCC xenograft models revealed that restoring SHQ1 levels enhanced the anti-tumor activity of the endoplasmic reticulum (ER) stress inducer tunicamycin (TM) and common chemotherapy drug paclitaxel (PTX)." (PMID 32522979, 2020). "Taken together, these studies demonstrate that presence of SHQ1 enhances tumor sensitivity via facilitating to chemotherapy." (PMID 32522979, 2020). "In HCC tissues from patients, expression of SHQ1 was significantly decreased in the tumor compared to adjacent tissues." (PMID 32522979, 2020). "SHQ1 positively regulates UPR for promoting tumor-suppressive effects in a variety of solid tumor cells." (PMID 32522979, 2020). "In the persistent ER stress conditions of a HepG2 xenograft tumor model, SHQ1-mediated hyper-activation of ER-sensor signaling induces apoptosis." (PMID 32522979, 2020). "We here provide mechanistic evidence demonstrating regulation of MYC splicing by SHQ1 as an important event involved in T-cell leukemogenesis, thus revealing the tumor-supporting role of SHQ1 in human cancers that links SHQ1 to RNA splicing and leukemogenesis." (PMID 30323192, 2018). "We also identify MYC, whose splicing and expression are highly dependent on SHQ1, as an important downstream effector mediating the tumor-supporting role of SHQ1." (PMID 30323192, 2018). "Third, somatic mutations have been reported across a range of human tumor types in several genes within the locus (FOXP1, RYBP, SHQ1)." (PMID 29057879, 2017). "The work presented here establishes that the 3p13-14 locus from FOXP1 to SHQ1 has tumor suppressor activity in the context of PI3K pathway activation conferred by PTEN loss." (PMID 29057879, 2017). "Altogether, these results revealed SHQ1 inhibited tumor growth upon ER stress." (PMID 32522979, 2020). "Taken together, SHQ1 promotes ER-stress-induced tumor apoptosis via PERK-signaling pathway." (PMID 32522979, 2020). "We also show that SHQ1 promotes tumor apoptosis and sensitizes cells to chemotherapeutics." (PMID 32522979, 2020). "Based on these data from various tumor types, we reason that SHQ1 may exert variable or even opposing roles in different tumor contexts." (PMID 30323192, 2018). "Treatment with TM caused a decreased apoptosis in tumor tissues lacking the SHQ1." (PMID 32522979, 2020). "The SHQ1-KD tumor xenografts were significantly more resistant to PTX than the controls, as determined by increased tumor volume and tumor weight in this group." (PMID 32522979, 2020). "Indeed, tumor growth, and resistance to drug-induced apoptosis are enhanced in HepG2 xenograft tumors lacking SHQ1." (PMID 32522979, 2020).
cancer (6 papers, 2011 to 2024). A tumor composed of atypical neoplastic, often pleomorphic cells that invade other tissues. "Using T-ALL as a model system, we reveal a molecular mechanism underlying SHQ1 expression in human cancers." (PMID 30323192, 2018). "Based on our results, Combination of SHQ1 with chemotherapy drugs may be a new strategy to improve cancer therapy." (PMID 32522979, 2020). "There is need to understand the biological activities of SHQ1 in the context of cancer." (PMID 32522979, 2020). "In light of this, activation of SHQ1 might be a desirable approach for targeting some cancers." (PMID 32522979, 2020). "Regulatory mechanism and functional role of SHQ1 in human cancers are largely unknown." (PMID 30323192, 2018). "ATAD2, BRMS1L, PUF60, SHQ1, and USP4 were found to influence overall survival in 15, 9, 13, 13, and 12 of the 21 cancer types, respectively." (PMID 39127727, 2024). "Thus, the mechanisms of SHQ1 in cancers remain largely unknown." (PMID 32522979, 2020). "Despite well-documented mechanism of SHQ1 in H/ACA snoRNP biogenesis, little is known about its precise functional role, especially in human diseases such as cancer." (PMID 30323192, 2018). "From these samples, we identify established driver aberrations in a cancer-related gene in nearly all cases (97.7%), including driver gene fusions (TMPRSS2:ERG), driver focal deletions (PTEN, RYBP and SHQ1) and driver amplifications (AR and MYC)." (PMID 27328849, 2016). "Survival analysis showed that several of the dysregulated genes (e.g. ATAD2, BRMS1L, PUF60, SHQ1, and USP4) have an impact on prognosis in multiple cancer types, thereby further highlighting the clinical significance of aberrant gene expression patterns on patient survival." (PMID 39127727, 2024).
neurological disorder (4 papers, 2017 to 2024). "Here we investigated two compound heterozygous variants in human SHQ1 that were identified in a child presenting severe neurological disorder." (PMID 37818102, 2023).
SHQ1 also shares sentences with these, for which no sentence is quoted: dyskeratosis congenita (2 papers); Hoyeraal-Hreidarsson syndrome (2); bladder urothelial carcinoma (1); cervical cancer (1); chronic myeloid leukemia (1); head and neck cancer (1); melanoma (1); neurodevelopmental disorder (1); prostate adenocarcinoma (1); seizure disorder (1); Splenomegaly (1).